MYL10 (myosin light chain 10)
Synonyms: MYLC2PL; PLRLC; MGC3479
Tractability: No criterion of Open Targets' tractability assessment is met for any kind of drug.
Gene: Protein-coding gene on chromosome 7 (101,613,330 to 101,629,296, reverse strand). Ensembl gene ENSG00000106436.
Subcellular location (Human Protein Atlas): Microtubules
Pathways (Reactome):
Muscle contraction: Smooth Muscle Contraction
Gene Ontology:
Molecular function: protein binding; calcium ion binding
Cellular component: mitochondrion; cytoplasm; cytosol
Genetic constraint (gnomAD): Loss-of-function variants: 15 observed, 20.83 expected, observed/expected ratio (o/e) 0.72, 90% interval 0.48 to 1.11. The upper end of that interval is the gene's LOEUF score, 1.11, which puts it in group 4 of 6, group 1 being the genes least tolerant of losing a copy. Missense variants: 209 observed, 232.14 expected, observed/expected ratio (o/e) 0.9, 90% interval 0.8 to 1.01. Synonymous variants: 82 observed, 82.11 expected, observed/expected ratio (o/e) 1, 90% interval 0.83 to 1.2.
Homologues: Orthologues: chimpanzee MYL10 (100% identical), macaque MYL10 (97% identical), rat Myl10 (77% identical), dog MYL10 (72% identical), pig MYL10 (72% identical), rabbit MYL10 (70% identical), mouse Myl10 (65% identical), guinea pig MYL10 (64% identical), zebrafish myl10 (55% identical), Caenorhabditis elegans mlc-1 (35% identical), Caenorhabditis elegans mlc-2 (35% identical). Paralogues in human: MYL2 (59% identical), MYL11 (54% identical), MYL5 (49% identical), MYL7 (46% identical), MYL9 (42% identical), MYL12A (41% identical), MYL12B (41% identical).
Diseases named in the same sentence as MYL10 in open-access papers:
MYL10 is named in the same sentence as 8 diseases in open-access papers, as found by Europe PMC text mining. Sharing a sentence is not in itself a finding about the gene and the disease. The quoted sentences say what the papers report.
Salmonella Infections (1 paper, 2023). Infections with bacteria of the genus SALMONELLA. "ENSGALG00000048475, FLNA, MYL10, and IL18 were enriched in terms of Salmonella infection." (PMID 37761904, 2023).
MYL10 also shares sentences with these, for which no sentence is quoted: breast carcinoma (2 papers); cardiac hypertrophy (1); cardiomyopathy (1); cardiovascular disease (1); Insulin resistance (1); melanoma (1); viral myocarditis (1).